MTOR (mechanistic target of rapamycin kinase)
Diseases named in the same sentence as MTOR in open-access papers (continued):
Sharing a sentence is not in itself a finding about the gene and the disease.
colitis (continued). "Additionally, mTOR activation is vital for functional intestinal epithelial repair, demonstrated in models of ischemia-reperfusion injury, radiation-induced damage, and colitis." (PMID 39684390, 2024). "Infection of a colitis-susceptible mouse model with C. jejuni activated mammalian target of rapamycin (mTOR) signaling, intestinal inflammation, neutrophil infiltration, and severe colitis, which could be reversed by administering rapamycin and activating autophagy." (PMID 36071979, 2022). "Thus, hypoxia might regulate the development of colitis by downregulating the NLRP3/mTOR pathway and activating autophagy in the colon of Crohn’s disease patients and mice with colitis." (PMID 33808793, 2021). "In addition to mTOR, the phosphatidylinositol 3-kinase-γ (PI3K-γ, upstream of mTOR) have been shown to modulate C. jejuni-induced colitis independently of T cell activation by recruitment of neutrophilic granulocytes to the infected intestines and subsequent massive TNF secretion." (PMID 32231139, 2020). "mTOR also inhibits the anti-inflammatory effect of glucocorticoids in myeloid immune cells, but the role of mTOR signaling in the immune regulation of glucocorticoid-treated colitis remains unclear." (PMID 32290362, 2020). "Moreover, Gln has protective effects in colitis by mTOR signaling pathway." (PMID 29682569, 2018). "In support of this hypothesis, uptake of amino acids and hence activation of mTOR are required for the maintenance of intestinal homeostasis, whereas malnutrition or suppression of mTOR activity induces colitis due to dysregulated innate immune functions of the intestine." (PMID 26439699, 2015). "mTOR hyperactivation induced necroptosis of the epithelium, disruption of the intestinal barrier, and sensitivity for DSS‐induced colitis." (PMID 40236773, 2025). "Treatment with mesalamine significantly reduced mTOR levels by 49.75% (F = 528.4, p = 0.004) and downregulated NLRP3 expression by 40.32% (F = 66.14, p = 0.008) compared to the colitis group." (PMID 40387460, 2025). "Procyanidin A can also influence DSS-induced colitis in mice, procyanidins exert their activity in the AMPK/mTOR/p70S6K pathway by decreasing levels in p-p70S6K and p-mTOR in this pathway." (PMID 39494333, 2024). "In a mouse model of DSS-induced colitis, pharmacological or genetic inhibition of TREM-1 has been shown to enhance macroautophagy and chaperone-mediated autophagy via mTOR dysregulation, thereby reducing endoplasmic reticulum stress and suppressing colitis." (PMID 38790914, 2024). "L-theanine suppressed the expression levels of TNF-α, IL-1β, IL-6, iNOS, and COX-2 in DSS-induced colitis, and relieved phosphorylation of GSK-3β and Akt/mTOR in Cd-induced ICR mice." (PMID 39572022, 2024). "After colitis is induced by lipopolysaccharide in mice, the upstream Toll-like receptor 4 (TLR4) signaling pathway activates mTOR and inhibits autophagy." (PMID 36840593, 2023). "In the chronic murine TNBS model, dapagliflozin relieves colitis by increasing colonic autophagy and repressing apoptosis through activation of AMPK/mTOR and Nrf2/HO-1 pathways and suppression of the HMGB1/RAGE/NF-κB cascade (Arab, Al-Shorbagy, y Saad, 2021)." (PMID 37397491, 2023). "Meanwhile, procyanidin treatment activated the AMPK/mTOR/p70S6K signal pathway, thus alleviating DSS-induced colitis by promoting cell proliferation." (PMID 37298531, 2023). "Investigation of the molecular mechanism responsible for colitis improvement revealed that aloperine treatment in Jurkat cells attenuated the levels of p-PI3K p85, p-Akt, and p-mTOR (major molecules of PI3K/Akt/mTOR pathway)." (PMID 35453655, 2022). "Metformin also increased the level of SMILE and suppressed that of mTOR and STAT3 in colon tissue of DSS-induced compared to vehicle-treated DSS-induced colitis mice." (PMID 34211461, 2021). "Our findings also suggest an interaction between the PI3K-Akt-mTOR pathway and LAM synthesis in colitis-induced carcinogenesis." (PMID 34359585, 2021).
colitis (continued). "The colon tissue from DSS-induced SMILE transgenic colitis mice showed increased levels of SMILE and AMPK and decreased levels of mTOR and STAT3 compared to the colon tissue of wild-type DSS-induced colitis mice." (PMID 34211461, 2021). "The colon tissue from SMILE overexpressing DSS-induced colitis mice exhibited higher levels of SMILE and AMPK and lower levels of mTOR and STAT3 than that of mock vector-treated mice." (PMID 34211461, 2021). "In colon from DSS-induced colitis mice, the level of p-AMPK was decreased and the level of p-mTOR and p-P70S6K were increased in CB2R KO group when compared with those in WT group." (PMID 27611972, 2016). "In this research, we investigate the anti-inflammatory effects of AZD8055, a potent mTOR inhibitor, on T cell response in dextran sulfate sodium (DSS)-induced colitis in mice, a commonly used animal model of inflammatory bowel diseases (IBD)." (PMID 27128484, 2016). "A recent report showed reduced colitis severity by treatment with the macrolide 7-O-succinyl macrolactin A (SMA), which was mediated in part through inhibiting TNF-induced PI3K, AKT, mTOR and p70S6 kinase phosphorylation." (PMID 27997590, 2016). "Similarly, PTX treatment resulted in significant reductions of 50.08% in mTOR (F = 528.4, p = 0.02) and 53.93% in NLRP3 expression (F = 66.14, p = 0.006) versus the colitis group." (PMID 40387460, 2025). "Several experimental studies have investigated the therapeutic potential of PTX in models of colitis; however, the present study is the first to elucidate its modulatory effects on the SPHK1/S1P, IL‐6/STAT3, AMPK/mTOR/NLRP3, and ZO‐1 signaling pathways in experimental colitis." (PMID 40387460, 2025). "However, in IBD and murine colitis, hypoxia-driven HIF-1α in macrophages activates Wnt/mTOR pathways, disrupting autophagy in IEC." (PMID 38605960, 2024). "However, hypoxia counteracts inflammation through the downregulation of the binding of mTOR and NLRP3 and the activation of autophagy, which is protective in mouse models of colitis." (PMID 37830626, 2023). "The STAT3 and mTOR pathways have also been demonstrated to promote Th1 cells producing IL-10 by using butyrate to deal with the T cells from IBD patients and the DSS model, therefore limiting colitis." (PMID 37371485, 2023). "In the same context, the inhibition of the mammalian target of rapamycin (mTOR), a downstream molecule of PI3K/AKT pathway, has also been proven to afford significant anti-inflammatory actions against colitis progression through dampening the T-cell function and NF-κB activation." (PMID 37111290, 2023). "In contrast, the blockade of NLRP3 did not impact the severity of colitis, while the inhibition of mTOR resulted in the exacerbation of DSS-induced colitis in VAD mice." (PMID 37240022, 2023). "The expression of mTOR in intestinal epithelial cells was higher than that in intestinal immune cells, and Dex treatment significantly increased the expression of mTOR in intestinal epithelial cells in DSS-induced colitis." (PMID 32290362, 2020). "The activation of mTOR in the context of colitis was not specific to the TCT model; we found that mTOR was activated in multiple genetic models of IBD and in a subset of human IBD patients." (PMID 29596476, 2018). "While long-term rapamycin treatment revealed a key role for mTOR in the maintenance of colitis, chronic inhibition does not provide mechanistic insight into the potential role that epithelial mTOR plays in this complex, tissue-level phenotype." (PMID 29596476, 2018). "However, high concentration of BCAAs increases oxidative stress and inflammation by mTOR and NF-κB; thus, diets with low Leu ameliorate symptoms of colitis and intestinal inflammation via the amino acid sensor GCN2 in colitis model." (PMID 29682569, 2018).
colitis (continued). "Next, we observed that AA-diet-fed mice that received rapamycin during diet consumption showed no sign of colitis exacerbation suggesting that mTOR activation was involved in the mechanism by which AA diet triggered inflammation and exacerbation of colitis." (PMID 29209321, 2017). "Additionally, mTOR and STAT3 pathways and their crosstalk are significantly upregulated in patients with IBD and inhibition of mTOR ameliorated DSS-induced colitis." (PMID 27144580, 2016). "Additionally, we used a potent and specific mTOR inhibitor, rapamycin, to determine whether the promotion of autophagosome formation can prevent the exacerbation of DSS-induced colitis in VAD mice." (PMID 37240022, 2023). "Additionally, different doses of Dex significantly upregulated p-mTOR and p-AKT (Thr308), which are downstream targets of mTORC1, but not p-AKT (Ser473), which is a downstream target of mTORC2, in CD45- cells from colon tissue in DSS colitis mice." (PMID 32290362, 2020). "In a rat colitis model, the potential therapeutic anti-inflammatory/antioxidant activity of mango involves inhibition of cyclooxygenase (COX-1 and COX-2) by proanthocyanidin, inhibition via tumor necrosis factor (TNF)-α, IGF-1/mTOR pathway, as well as PI3K/Akt/mTOR pathway." (PMID 33167456, 2020). "Furthermore, aloperine inhibited PI3K/Akt/mTOR signaling and upregulated PP2A expression in the DSS-induced colitis mice and in Jurkat cells, but LB-100 (PP2A inhibitor) resulted in an elevated Akt activity in Jurkat cells, activated T-cells, and human splenic mononuclear cells." (PMID 29056830, 2017). "Interestingly, although Tsc2, an upstream regulator of mTOR signaling, has also been shown to regulate Notch, we could not find any evidence in our protein or gene expression data indicating that Notch signaling, in addition to mTOR signaling, is activated in the TCT model of colitis." (PMID 29596476, 2018). "As the absence of mTOR-mediated signaling reduced ILC3s’ capacity to secrete IFN-γ upon IL-23 stimulation, we next wished to probe whether RptorΔRORγt and/or RictorΔRORγt mice develop colitis following α-CD40 Ab treatment." (PMID 34341503, 2021).
autoimmune disease (99 papers, 2010 to 2026). A disorder resulting from loss of function or tissue destruction of an organ or multiple organs, arising from humoral or cellular immune responses of the individual to their own tissue constituents. "In autoimmune diseases, immune cell activity is often excessive; therefore, mTOR inhibition can potentially limit effector T-cell-associated inflammation." (PMID 39996755, 2025). "Accordingly, aberrant PI3K/AKT/mTOR signaling has been implicated in the defective selection of autoreactive B cells, increasing the risk of autoimmune disease." (PMID 39917832, 2025). "Genetic polymorphisms predisposing individuals to autoimmune disease, however, tend to negatively influence autophagy downstream of mTOR, with the ATG16L1 and IRGM polymorphisms predisposing individuals to Crohn’s disease being a good example of this." (PMID 40563920, 2025). "Dysregulation of mTOR signaling has been reported to be associated not only with cancer but also with autoimmune disease, obesity, neurodegeneration, infectious diseases, and ageing." (PMID 36109789, 2022). "Rapamycin, an mTOR inhibitor used in autoimmune diseases and cancers also improves autophagy deficiency and has renal protective effects in DKD." (PMID 34744742, 2021). "The mTOR pathway plays an important role in autoimmune diseases and is closely associated with miRNAs." (PMID 34721589, 2021). "Activation of mTOR is a hallmark of and biomarker in autoimmune diseases, such as systemic lupus erythematosis (SLE) and ITP." (PMID 32296709, 2020). "Deregulation of mTOR signaling has been shown that it is closely associated with cancers and metabolic diseases as well as autoimmune diseases." (PMID 28349073, 2017). "It has been shown that activation of the mTOR signaling pathway is a positive regulator of CD4+ effector T cell differentiation and a negative regulator of Treg (regulatory T cell) differentiation, and that mTOR hyperactivation is associated with the pathogenesis of a number of autoimmune diseases." (PMID 41155356, 2025). "The new role of the NLRP3 inflammasome and the mTOR pathway as regulators of IL-1β and IgM in activated B-lymphocytes studied here offers a potential new strategy to treat autoimmune disease in which IL-1β and pathogenic IgM antibodies may play a role, particularly if triggered by infectious agents." (PMID 29170665, 2017). "In this context, mTOR inhibition by rapamycin —approved by the FDA for the prophylaxis of organ transplant rejection, cancer, and certain autoimmune diseases — has been primarily associated with its effects on autophagy." (PMID 40450326, 2025). "Currently, therapeutic modulation of the mTOR pathway is seen as a promising strategy for inducing remission in patients suffering from autoimmune diseases, and rapamycin treatment has been first tested and has shown some beneficial effects." (PMID 40806725, 2025). "mTOR signaling integrates metabolic and immune signals to promote Th17 cell development, highlighting its potential as a therapeutic target in autoimmune diseases." (PMID 40563411, 2025). "While our model requires further investigation, it holds potential for manipulating the intensity of PI3K/AKT/mTOR signaling to guide the type of memory generated during vaccination or in therapeutic interventions for autoimmune diseases." (PMID 39917832, 2025). "Rapamycin, a Food and Drug Administration (FDA)-approved drug for autoimmune diseases, was chosen as the mTOR inhibitor for in vitro and in vivo study." (PMID 41049011, 2025). "Studies have shown that activation of the PI3K/Akt/mTOR and rap 1 pathways in lymphocytes alters the development of systemic autoimmunity, establishing a connection between this pathway and autoimmune diseases." (PMID 38967046, 2024). "Dysregulation of mTOR has been associated with numerous diseases including cancer, fibrosis, COPD, cardiovascular disease, autoimmune diseases, and metabolic disease." (PMID 38711460, 2024).
autoimmune disease (continued). "By inhibiting mTOR, these complexes can suppress the immune response, which can be beneficial in preventing organ transplant rejection and treating autoimmune diseases." (PMID 38474110, 2024). "Sirolimus is an FDA-approved mTOR inhibitor commonly used in renal transplant recipients to prevent allograft rejection and has demonstrated efficacy in treating autoimmune diseases." (PMID 37159282, 2023). "It is an important finding for clinicians because mTOR inhibitors are being tested for autoimmune diseases." (PMID 37720230, 2023). "This study provides novel insights and targets to further explore the specific mechanisms by which Bcl-3 regulates the mTOR pathway, maintains immune homeostasis, and prevents inflammation and autoimmune diseases by targeting Bcl-3 molecules." (PMID 37794349, 2023). "Based on the fundamental findings, considerable clinical trials have attempted to apply mTOR inhibitors in therapeutic strategies for transplant rejection, tumor, autoimmune diseases, etc. and presented promising prospects." (PMID 38164133, 2023). "Other T cell correlates with autoimmune disease include reduced frequencies of naïve T cells, accumulation of effector and memory T cells, mTOR activation, and elevated levels of inflammatory cytokines." (PMID 36311777, 2022). "We also identified enhanced signaling mediated by mTOR, a primary regulator of metabolic reprogramming in T cells and a key driver in T-cell mediated autoimmune diseases." (PMID 36159832, 2022). "The mTOR inhibitors are a family of compounds that are being used for treating several human diseases such as cancer, autoimmune diseases and neurodegeneration." (PMID 36109789, 2022). "L-Leucine is proven to join the mTOR pathway to increase Tregs and potentially treat autoimmune diseases." (PMID 35360108, 2022). "Rapamycin is a novel immunosuppressant with significant efficacy in autoimmune diseases and against organ transplantation rejection; as a targeted inhibitor of mTOR, the drug can also inhibit the proliferation and growth of tumor cells." (PMID 36612173, 2022). "AKT1 is an essential regulator in AKT1/mTOR signaling pathways, and this pathway in autoimmune diseases such as SS can regulate the IL-17 effect." (PMID 36248435, 2022). "This further suggests an intriguing role of mTOR modulation for the treatment of autoimmune disease including RRMS." (PMID 36504430, 2022). "Reduced SRSF1 expression in T cells is correlated with autoimmune disease, hypersensitivity, and inflammation, and these phenotypes result in part from elevated mTOR activity." (PMID 35202654, 2022). "And, mTOR activation in T cells has been noted during the development of several autoimmune diseases such as SLE, MS and RA." (PMID 36311777, 2022). "Consistent with the use of rapamycin as an immunosuppressant, dysregulated mTOR signaling is involved in a variety of autoimmune diseases (AID)." (PMID 34065644, 2021). "Recent studies showed that mTOR pathway activation plays critical roles in the pathogenesis of autoimmune diseases, including RA, immune thrombocytopenia, T1D, large-vessel vasculitis, and SLE." (PMID 34065644, 2021). "Aberrant activation of mTOR signaling has been known to contribute to the pathogenesis of autoimmune disorders and cancer." (PMID 34899357, 2021). "mTOR is now well recognized as an important regulator of CD4+ T subsets that influences the development of autoimmune diseases such as MS and EAE." (PMID 32983109, 2020). "We summarized the existing metabolic targets used in DMARDS and highlighted several future potential targets to treat autoimmune diseases including mTOR, GCN2, IDO1, ARG 1, kynurenine, cysteine, S1P receptor and fatty acid enzymes." (PMID 32341806, 2020). "The mechanistic target of rapamycin (mTOR) pathway is increasingly recognized as one of the key drivers of proinflammatory responses in autoimmune diseases." (PMID 32341806, 2020).